NR2C2 (nuclear receptor subfamily 2 group C member 2)
Diseases named in the same sentence as NR2C2 in open-access papers (continued):
Sharing a sentence is not in itself a finding about the gene and the disease.
rectal adenocarcinoma (1 paper, 2025). "Our study shows that multiple immune genes associated with ASCC3, including JAK1, NFKB1, SEMA5A, NR2C2, CNTF and CREB1, positively impact the prognosis of rectal adenocarcinoma patients." (PMID 40881169, 2025). "ASCC3 is a specific protective factor for rectal adenocarcinoma across various cancer types, particularly in digestive system cancers, and can synergize with several immune-related genes, including JAK1, NFKB1, SEMA5A, NR2C2, CNTF, and CREB1, to influence patient prognosis." (PMID 40881169, 2025).
rectal cancer (1 paper, 2025). A primary or metastatic malignant neoplasm that affects the rectum. "The combination of ASCC3 with several immune-related genes, including JAK1, NFKB1, SEMA5A, NR2C2, CNTF and CREB1, plays a significant predictive role in the prognosis of rectal cancer patients." (PMID 40881169, 2025). "Additionally, our diagnostic and prognostic models, constructed using machine learning, highlight the significant predictive value of ASCC3 in combination with various immune-related genes, including JAK1, NFKB1, SEMA5A, NR2C2, CNTF and CREB1, for rectal cancer prognosis." (PMID 40881169, 2025).
steatosis (1 paper, 2023). Increased lipid within the cytoplasm of cells. "We then investigated whether PPARγ or NR2C2 mediated the effects of 9-HODE and 13-HODE on hepatocyte steatosis." (PMID 38071367, 2023). "We found that the knockdown of Pparg or Nr2c2 or both did not affect 9/13-HODE-induced hepatocyte steatosis." (PMID 38071367, 2023).
uveal melanoma (1 paper, 2025). A melanoma derived from melanocytes of the uveal tract. "NR2C2 was reported to bind the promoters of 9 downregulated lncRNAs in olaparib-treated human uveal melanoma cells." (PMID 40218347, 2025).
viral infections (1 paper, 2025). "It is important to note that M1 macrophages in a bronchial asthma model exhibit an anti-inflammatory effect, while showing a proinflammatory effect during bacterial or viral infections, suggesting possible immunomodulatory effects of IRF5 and NR2C2." (PMID 41516283, 2025).
infection (43 papers, 2012 to 2025). The state of being infected such as from the introduction of a foreign agent such as serum, vaccine, antigenic substance or organism. "A few genes were downregulated 4 h after infection: caspase 8 (Casp8), nuclear receptor subfamily 2, group C, member 2 (Nr2c2/TAK1), mitogen-activated protein kinase 9 (Mapk9/JNK2) and interleukin 6 receptor-alpha (Il6ra)." (PMID 30555476, 2018).
tumor (33 papers, 2013 to 2025). "In this study, we observed a clear association between elevated NR2C2 expression and tumor invasion and recurrence." (PMID 31223310, 2019). "In vivo study also underlined that silencing NR2C2 inhibited tumor growth and prolonged life span in xenografted mouse model." (PMID 30518750, 2018). "Extensive research has demonstrated that NR2C2 potentially function as either a tumorigenic gene or a tumor-suppressive gene, depending on the type of tumors." (PMID 39751645, 2024). "In the 31 paired samples, NR2C2 was more highly expressed in the recurrent as compared to the primary tumor." (PMID 31223310, 2019). "NR2C2 is extensively expressed in the ovary, testis, and brain and regulates different aspects of neuronal development; it also induces tumor initiation under the control of various modulators." (PMID 31223310, 2019). "Large scale of studies have shown that NR2C2 played an important role in the development of tumor, such as lung cancer and prostate cancer." (PMID 30518750, 2018). "In vivo study showed that UCA1 knockdown and NR2C2-uORF overexpression combined with silenced NR2C2 produced a tumor of the smallest volume and resulted in the longest survival time in nude mice." (PMID 30518750, 2018). "Remarkably, lnc-UCA1 knockdown combined with uORF overepression and NR2C2 knockdown led to severe tumor suppression in vivo." (PMID 30518750, 2018). "In vivo studies further confirmed that UCA1 knockdown combined with uORF overexpression and NR2C2 silenced suppressed tumor growth greatly and led to the longest survival in a xenograft mouse model." (PMID 30518750, 2018). "The results demonstrated that EEF2, G3BP1, G3BP2, PRPF8, RECQL4, STOML2, and UBB exhibited significantly higher expression levels in the majority of tumor tissues, whereas METTL3 and NR2C2 showed a widespread downregulation trend." (PMID 41341921, 2025). "Since IRF3, a tumor suppressor, and E2F1 and NR2C2, cancer promoters, have been reported to be important in cancer, investigation of the action of KIAA1324 in the regulation of these target genes is essential for understanding KIAA1324-related cancer development deeply." (PMID 37612293, 2023). "NR2C2, MAPK8, PPARA, and PTGS2 are all downregulated in tumor versus normal tissues." (PMID 35814450, 2022).
cancer (25 papers, 2015 to 2025). A tumor composed of atypical neoplastic, often pleomorphic cells that invade other tissues. "Furthermore, we analyzed the mutation status of ASCC3, JAK1, NFKB1, SEMA5A, NR2C2, CNTF and CREB1 across pan-cancer." (PMID 40881169, 2025). "The upregulated DEGs showed various enforced transcription factors’ networks including IRF3, TAL1, JUN, and FOXA, whereas the downregulated DEGs demonstrated dramatic network suppression of E2F1, a cell cycle progressor, and NR2C2, a cancer-promoting orphan receptor." (PMID 37612293, 2023). "NR2C2 can inhibit cancer initiation, but promote cancer progression." (PMID 30809968, 2019). "In addition, we identified three heterozygous candidate missense variants in known cancer susceptibility genes (BMPR1A,BRIP1, and SRC), three truncating variants in possibly novel cancer genes (CLSPN,SEC24B, SSH2) and four candidate missense variants in ACACA, NR2C2, INPP4A, and DIDO1." (PMID 30809968, 2019). "‘Cancer’ was the most represented function, with 57 genes, including BDNF, NR2C2 and CADPS2 (1.99 × 10–8 < P < 1.23 × 10–2)." (PMID 26999292, 2016). "Among these, NR2C2 and PRPF8 were present in all five cancers." (PMID 39657701, 2024).
bacterial diseases (2 papers, 2024 to 2025). "On the other hand, NR2C2 is recognized for its proinflammatory effects during bacterial infections as it augments NFkB expression, thereby fostering the production of IL1B and IL6 in macrophages." (PMID 41516283, 2025).
NR2C2 also shares sentences with these, for which no sentence is quoted: diabetes (7 papers); fungal infection (4); ACTHomas (3); adenoma (3); metabolic disease (3); osteoporosis (3); anemia (2); atherosclerosis (2); cardiovascular diseases (2); Obesity (2); pituitary tumor (2); prostate tumor (2); adenocarcinoma (1); adrenal hypoplasia congenita (1); Anxiety (1); bladder tumor (1); blast (1); Cirrhosis (1); clear cell renal cell carcinoma (1); cutaneous T-cell lymphoma (1); delirium (1); digestive system cancer (1); erectile dysfunction (1); erythroleukemia (1); Granuloma (1); gynecological tumors (1); hematological disorder (1); hemoglobinopathies (1); Hepatic steatosis (1); Hyperglycemia (1).
A further 18 diseases each share a sentence with NR2C2 in 1 paper.